FGF23 (fibroblast growth factor 23)
Diseases named in the same sentence as FGF23 in open-access papers (continued):
Sharing a sentence is not in itself a finding about the gene and the disease.
chronic kidney disease (continued). "A retrospective analysis firstly revealed that FGF23 was significantly and independently associated with unstable plaques in patients with T2DM who underwent carotid endarterectomy, and similar results were also found in African-American T2DM patients without end-stage renal disease." (PMID 38622690, 2024). "Besides, FGF23 suppresses vitamin D activation and decreases PTH synthesis and secretion, the primary trigger of chronic kidney disease—mineral and bone disorders (CKD-MBD)." (PMID 35806367, 2022). "However, an additive effect between FGF23 and HP on inducing cardiac hypertrophy and energy metabolism changes was observed, indicating that end-stage renal disease (ESRD) or dialysis patients with hyperphosphatemia and high FGF23 levels may suffer more from myocardial hypertrophy." (PMID 32938919, 2020). "Moreover FGFR4−/−, FGFR4-G385R and wildtype mice on adenine diet are characterized by similar levels of hyperphosphatemia and comparable elevations of FGF23 suggesting that FGFR4 does not substantially contribute to the regulation of serum phosphate in chronic kidney disease." (PMID 31575945, 2019). "Fibroblast growth factor 23 (FGF23) has recently emerged as a powerful biomarker for adverse outcome in patients with or without chronic kidney disease (CKD)." (PMID 25902817, 2015). "On the other hand, elevated fibroblast growth factor 23 (FGF23) levels, may account, at least partly, for the dysregulation of monocytic CYP27B1 in uremia and, as such, may contribute to the high cardiovascular and infectious disease and immune system disorder in chronic renal failure." (PMID 28197428, 2012). "Biochemically, patients present with low circulating levels of fibroblast growth factor 23 (FGF23) and parathyroid hormone (PTH), likely resulting (at least partly) from tubular phosphate leak and in contrast to patients with chronic kidney disease (CKD) with a different primary diagnosis." (PMID 39540998, 2024). "FGF23 is a negative regulator of PTH mRNA expression and secretion and can be stimulated by non-oxidized PTH, particularly in the context of chronic kidney disease (CKD)." (PMID 38732094, 2024). "Not serum FGF23 but cardiac FGF23 levels and RAAS parameters significantly changed in the early stage of LVH without chronic kidney disease." (PMID 38174329, 2023). "This homeostasis is disrupted in patients with chronic kidney disease (CKD) due to disruption of normal homeostatic loops with kidney function decline, with compensatory changes in several hormones (parathyroid hormone - PTH, vitamin D, fibroblast growth factor 23 - FGF23)." (PMID 33107900, 2021). "The term “chronic kidney disease-mineral bone disorder” (CKD-MBD) has been used in humans and animals to describe a condition characterized by renal osteodystrophy and abnormal mineral metabolism with high levels of serum phosphate, fibroblast growth factor (FGF)-23, and parathyroid hormone (PTH)." (PMID 32677951, 2020). "As part of the analysis of patients with chronic kidney disease (CKD), ESKD or after transplant, 6 healthy subjects were given 2 days of Pi restricted diet and 3 days with Pi repleted diet, but no changes in the C-terminal FGF23 (cFGF23) fragment were found." (PMID 39601886, 2025). "In the absence of αKlotho, FGF23 signals through the FGF receptor 4, but at much higher concentrations that are only found in pathological states such as in chronic kidney disease (CKD) or systemic inflammation." (PMID 33416083, 2021). "The present study aimed to clarify the relationship between FGF23 and CAAC in patients with chronic kidney disease (CKD) who were not on dialysis." (PMID 23339433, 2013). "Thus, this review comprehensively summarizes preclinical and clinical reports of the roles of FGF23 on osteoporosis and chronic kidney disease–mineral and bone disease (CKD-MBD), with an emphasis on the local actions, as opposed to systemic actions, of FGF23 on the bone." (PMID 35269640, 2022).
hyperphosphatemia (447 papers, 2008 to 2026). Abnormally high level of phosphate in the blood. "The patient exhibited hyperphosphatemia with a biochemical profile consistent with FGF23 deficiency, including extremely low intact FGF23 and elevated C-terminal fragments." (PMID 41898628, 2026). "In humans, genetic deficiencies of klotho and of Fgf23 as well as the regulators of FGF23 production cause familial tumoral calcinosis, which is a rare genetic disease with hyperphosphatemia and ectopic calcifications." (PMID 40471241, 2025). "Hyperphosphatemia has been linked to aKlotho (aKL) deficiency, which is correlated with increased serum fibroblast growth factor‐23 (FGF23)." (PMID 39797505, 2025). "Loss of regulation of FGF23 results in hyperphosphatemia resulting in the characteristic tissue calcinosis deposits, especially in periarticular locations." (PMID 40330379, 2025). "In another TC mouse model, a Trp589Arg GALNT3 mutation was generated by N-ethyl-N-nitrosourea (ENU) mutagenesis, resulting in hyperphosphatemia associated with decreased intact FGF23 levels, increased 1α,25(OH)2D3 levels, and periarticular calcified masses." (PMID 40149415, 2025). "In contrast, uraemic risk factors comprise anaemia, hyperphosphataemia, hyperparathyroidism, elevated FGF-23 levels, sleep apnoea, and systemic inflammation." (PMID 41439051, 2025). "Relatedly, growth of renal cell carcinoma is claimed to depend on dysregulation of the FGF/FGF-receptor 1 (FGFR1) cell signaling pathway, yet pharmaceutical inhibition of this pathway blocks circulating levels of FGF23 and causes hyperphosphatemia." (PMID 40643473, 2025). "Hyperphosphatemia has been associated with increased incidence of infection in dialysis patients, possibly due to increased FGF23 levels." (PMID 39666728, 2024). "An association between hyperphosphatemia and nephrocalcinosis was previously reported in FGF23‐knockout mice." (PMID 38438128, 2024). "Previous studies suggest that klotho function and dysregulation of the FGF23-klotho pathway, causing hyperphosphatemia and endothelial dysfunction, are associated with the pathogenic mechanisms of CKD development and disease progression." (PMID 39113723, 2024). "Hyperphosphatemia was linked with several key regulators of renal vascular calcification, such as elevated levels of fibroblast growth factor 23 (FGF23) and decreased expression of Klotho." (PMID 39497801, 2024). "In the pathophysiology of CKD-MBD, the progression of renal dysfunction induces vitamin D deficiency, hyperphosphatemia related to elevated fibroblast growth factor 23 (FGF23), excessive oxidative stress, and hyperparathyroidism." (PMID 39388484, 2024). "While deficiency or impaired actions of FGF23 cause hyperphosphatemia and soft tissue mineralization (ectopic calcification), elevated FGF23 levels result in renal phosphate wasting and impaired skeletal mineralization." (PMID 38530370, 2024). "The complex environment of hyperphosphatemia, FGF23 excess, and vitamin D deficiency accelerates the development of hypertension, vascular calcification, and left ventricular hypertrophy." (PMID 37422767, 2024). "On the other hand, hyperphosphatemia impairs hemoglobin levels via the overproduction of FGF23, in turn associated with iron deficiency." (PMID 39407717, 2024). "Hyperphosphatemia causes FGF23 release from osteocytes leading to a decrease in phosphate resorption and active excretion of phosphate by the kidney causing hypophosphatemia." (PMID 39301310, 2024). "Short-term use of the phosphate binder ferric citrate was shown to ameliorate iron deficiency anemia and hyperphosphatemia, and reduce FGF23 levels in CKD patients." (PMID 39666728, 2024). "This risk is linked with hyperphosphatemia, hyperparathyroidism, and elevated fibroblast growth factor-23 (FGF-23)." (PMID 39697967, 2024).
hyperphosphatemia (continued). "Considering that dialysis patients are anuric, in this population, the over-secretion of the two hormones results in hyperphosphatemia, which, via FGF23, results in iron deficiency and anemia." (PMID 39407717, 2024). "In dogs with azotemic CKD, an increased FGF-23 concentration was associated with an increased risk of premature death alongside other previously identified prognostic markers such as proteinuria, hyperphosphatemia, advanced CKD stage, and body condition score." (PMID 37893926, 2023). "This and other genetic causes of FGF23 excess and deficiency cause severe hypo- and hyperphosphatemia, respectively." (PMID 36821389, 2023). "Several diverse factors contribute to the development of osteoporosis in patients with CKD, including hypocalcemia, hyperphosphatemia, active vitamin D deficiency, increased parathormone, increased fibroblast growth factor 23, among others." (PMID 36773217, 2023). "Bi‐allelic loss‐of‐function GALNT3 mutations alter FGF23 metabolism, resulting in hyperphosphatemia and causing familial tumoral calcinosis (FTC)." (PMID 36824040, 2023). "In hyperphosphatemia, high levels of intact parathyroid hormone (iPTH) and fibroblast growth factor (FGF)-23 with reduced vitamin D concentration cause calcium release from bones, which triggers the calcification of vasculatures and weakens the bones." (PMID 37241191, 2023). "In summary, Col4a3−/− mice not only demonstrate hyperphosphatemia and excess FGF23 levels but also lung-associated airway pathology, including inflammation and remodeling." (PMID 36966182, 2023). "In humans, loss-of-function mutations in FGF23 or αKLOTHO are associated with elevated circulating 1,25(OH)2D levels and subsequent hypercalcemia and hyperphosphatemia, leading to progressive soft tissue calcifications." (PMID 36501215, 2022). "Elevated FGF23 levels can cause hypophosphatemia and rickets and decrease the levels of 1,25(OH)2D, whereas excessively low levels of FGF23 can hyperphosphatemia and soft tissue calcification and increase the levels of 1,25(OH)2D." (PMID 36353239, 2022). "Elevated levels of FGF23 are usually found in patients with renal failure, due to P retention and hyperphosphatemia, and FGF23 has been reported as a risk factor of cardiovascular mortality both in patients with CKD and in healthy individuals." (PMID 35268016, 2022). "Rare human mutations causing a severe deficiency of either Klotho or FGF23 are associated with hyperphosphatemia beginning at an early age." (PMID 35903083, 2022). "Although progressively increasing FGF23 concentrations in CKD help to mitigate hyperphosphatemia, elevated FGF23 levels have been independently associated with a multitude of adverse “off-target” effects, including faster CKD progression." (PMID 35461329, 2022). "Hyperphosphatemia, vitamin D deficiency, hyperparathyroidism, and high serum fibroblast growth factor 23 (FGF23) levels were found to predict CKD progression." (PMID 36292159, 2022). "A deficiency of either Klotho or FGF23 in mice results in excessive 1α-hydroxylase activity, overproduction of active vitamin D, and associated hyperphosphatemia and hypercalcemia." (PMID 35903083, 2022). "Klotho deficiency is associated with reduced renal function, hyperphosphatemia, increased FGF23 levels, renin–angiotensin–aldosterone system (RAAS) activation, inflammation, and chronic complications such as ectopic calcification, among others." (PMID 35887617, 2022). "Loss of renal klotho levels in patients with CKD-MBD is parallel to hyperphosphatemia, osteodystrophy, and vitamin D deficiency and is negatively associated with FGF23 levels." (PMID 35656113, 2022). "Risk factors include hypertension, increasing age, hyperphosphatemia and calcium load, secondary hyperparathyroidism, vitamin D deficiency, increased FGF-23, and uremia." (PMID 35453928, 2022).
hyperphosphatemia (continued). "So, in CKD patients, Klotho deficiency hampers FGF23 production, and the hyperphosphatemia resulting from it is one of the long-term consequences of CKD as well as vitamin D deficiency." (PMID 35812534, 2022). "With increasing kidney impairment also derangements of phosphate homeostasis arise, with increasing fibroblast growth factor 23 (FGF23) preceding hyperphosphatemia, both associated with increased cardiovascular risk, arterial stiffness, and mortality." (PMID 36096824, 2022). "Hyperphosphatemia occurs in late CKD stages despite increasing levels of FGF-23 due to klotho deficiency/resistance." (PMID 35566509, 2022). "Although progressively increasing FGF23 concentrations in CKD help to prevent or mitigate hyperphosphatemia, elevated FGF23 levels have also been independently associated with a multitude of adverse “off-target” effects." (PMID 35237863, 2022). "Decreased FGF-23 and hyperphosphatemia in mice have been shown to be associated with emphysema and vascular calcification, among other signs of ageing." (PMID 35263363, 2022). "FGF23 has been identified as an early biomarker of impaired kidney function, as FGF23 levels rise prior to the development of hyperphosphatemia, 1,25-(OH)2D3 deficiency, hypocalcemia, or secondary hyperparathyroidism." (PMID 34330955, 2021). "Our analysis showed that hypocalcemia, hyperphosphatemia, hyperparathyroidism, vitamin D and klotho deficiency, increased concentration of FGF-23, and abnormal bone mineralization and turnover contribute to the development of osteoporosis in patients with CKD." (PMID 34692259, 2021). "Hyperphosphataemia is caused by phosphate overloading and results in increased FGF-23 activity, decreased 1α,25[OH]2D production, and increased renal phosphate excretion." (PMID 34360534, 2021). "Hyperphosphatemia, reflecting diminished glomerular phosphate (Pi) clearance, coupled with a compensatory increase in fibroblast growth factor 23 (FGF23) secretion are thought to be key mediators of this risk." (PMID 34359914, 2021). "Prognosis was poor in the group with hyperphosphatemia at the initiation of dialysis, and an increased FGF23 level was a risk factor of mortality." (PMID 34069053, 2021). "The increased serum FGF23 level in ESRD patients was associated with hyperphosphatemia and hyperparathyroidism." (PMID 34721981, 2021). "In our study, FGF‐23 was significantly associated with subsequent development of hyperphosphatemia, and their relationship remained significant even after adjusting for CKD stage." (PMID 34418162, 2021). "In conclusion, increased serum FGF‐23 concentration was a significant risk factor for the subsequent development of hyperphosphatemia in normophosphatemic dogs with CKD." (PMID 34418162, 2021). "We found that increased serum FGF‐23 concentrations were significantly associated with risk of subsequent hyperphosphatemia and CKD progression in normophosphatemic dogs." (PMID 34418162, 2021). "Mice deficient in Klotho or fibroblast growth factor 23 (FGF23) manifest a premature aging syndrome associated with hyperphosphatemia, which can be rescued by reducing blood phosphate levels with dietary interventions." (PMID 34439556, 2021). "Klotho-deficient mice are characterized by hyperphosphatemia and enormously increased levels of serum FGF-23." (PMID 34867481, 2021). "Clinically, the importance of the FGF23/klotho and S-klotho actions to attenuate the mortality risks associated with hyperphosphatemia were demonstrated in CKD patients stages 3–4." (PMID 34950686, 2021). "The present study revealed that elevated serum FGF23 level in ESRD patients was associated with hyperphosphatemia, hyperparathyroidism and hypovitaminosis D, resulting in demyelination and demineralization of the cochlea." (PMID 34721981, 2021). "Serum FGF‐23 concentration >528 pg/mL was associated with a shorter time to development of hyperphosphatemia (P < .001) and CKD progression (P < .001)." (PMID 34418162, 2021).
hyperphosphatemia (continued). "The hyperphosphatemia and high-normal calcium seen with intact FGF23 deficiency or resistance leads to an increased calcium × phosphate product, which likely contributes to ectopic calcifications." (PMID 32457699, 2020). "The hyperphosphatemia observed in PT-PTH1RKL−/− mice was associated with elevated circulating FGF23, PTH, decreased circulating 1,25D and increased Npt2a." (PMID 32982979, 2020). "Perturbations in Fgf23 signaling are linked to multiple pathologies that involve bone, as low levels of Fgf23 characterize Hyperphosphatemia and soft tissue calcification disorders." (PMID 33057033, 2020). "On the other hand, FGF23 antibody treatment caused mineral disturbances, in particular hyperphosphatemia and was associated with increased mortality in a CKD rat model." (PMID 32150864, 2020). "Current literature supports such a thesis, and has indicated that the development and progression of CKD is significantly associated with a dysregulated FGF23-Klotho pathway, resulting in hyperphosphatemia and endothelial dysfunction." (PMID 32982966, 2020). "Both FGF23 deficiency and ppGalNAc-T3 deficiency cause the development of familial tumoral calcinosis because reduced circulating FGF23 levels cause hyperphosphatemia." (PMID 33218200, 2020). "Tumoral calcinosis has been reported in one young child with Hartsfield Syndrome due to a heterozygous inactivating variant in FGFR1; however, the degree of hyperphosphatemia and FGF23 resistance in that patient is unclear." (PMID 32457699, 2020). "Secondary hyperparathyroidism developed by 20 weeks of age and caused hyperphosphatemia, which increased plasma FGF‐23 levels with phosphaturic action." (PMID 32617522, 2020). "Patients develop either deficiency of or resistance to FGF23, leading to hyperphosphatemia and ectopic calcifications." (PMID 32457699, 2020). "The phenotypic characteristics of genetic Klotho deficiency, such as bone disease, VC, CVD increased FGF23 levels, hyperphosphatemia, and premature mortality, resembles the uremic accelerated aging phenotype in man." (PMID 32982966, 2020). "Another HFTC mouse created by ENU mutagenesis harbors a Trp589Arg mutation in Galnt3, and also has hyperphosphatemia with decreased intact FGF23 levels, elevated 1,25D, and subtle periarticular calcifications." (PMID 32457699, 2020). "In contrast to the controversially discussed role of FGF23 in the development of VC, hyperphosphatemia is strongly associated with VC." (PMID 31698866, 2019). "Considering that FGF23 is unable to normalize serum Pi levels in hyperparathyroidism and that inactivating mutations of FGF23 cause hyperphosphatemia despite the presence of PTH, both hormones appear to be necessary to maintain Pi homeostasis." (PMID 30972027, 2019). "This phenotype is also observed in 2- and 4-week ADE-treated mice and in a mouse model with partial deletion of klotho in distal tubular segments (Ksp-KL−/−), which is associated with hyperphosphataemia and elevated FGF23." (PMID 30393837, 2019). "Both Klotho and FGF23 deficient mice develop hyperphosphatemia and high serum levels of active 1,25-dihydroxyvitamin D levels together with premature aging features." (PMID 31546756, 2019). "Elevated FGF23 levels and hyperphosphatemia are risk factors for the excessively increased cardiovascular mortality in CKD patients." (PMID 31698866, 2019). "In the renal tubule, a low expression of transmembrane-α-klotho is generally associated with kidney tubular cell resistance to FGF23 leading to hyperphosphatemia." (PMID 30393837, 2019). "Treatment of FGF23 levels alone is inappropriate for CKD patients because it reinforces hyperphosphatemia and the associated toxic effects." (PMID 31698866, 2019). "In this syndrome, there is a loss of FGF-23 activity resulting in hyperphosphatemia, elevated 1,25-dihydroxyvitamin D levels, ectopic and vascular calcifications, and premature death." (PMID 30087898, 2018).